CASP8 (caspase 8)
Diseases named in the same sentence as CASP8 in open-access papers (continued):
Sharing a sentence is not in itself a finding about the gene and the disease.
Salmonella Infections (15 papers, 2014 to 2025). Infections with bacteria of the genus SALMONELLA. "This is entirely consistent with recent literature where Salmonella infection of macrophages reportedly caused recruitment of caspase-8 to an ASC inflammasome." (PMID 24790078, 2014). "As well, phosphorylation of STAT1 has been reported in acute mouse toxoplasmosis and Salmonella infection with activation of caspase 8 and host cell death." (PMID 37759313, 2023). "During Salmonella infection, caspase-8 can be recruited to the NLRC4 inflammasome regulating IL-1β secretion, but not playing a role in cell death." (PMID 36532444, 2022). "To investigate this, we generated Casp1–/–;Casp8–/–;Ripk3–/– iBMDMs and compared their death kinetics upon Salmonella infection to those of Casp1–/–;Casp11–/–;Casp12–/–;Casp8–/–;Ripk3–/– cells." (PMID 32735843, 2020). "Recently, caspase-8 has been shown to negatively regulate necroptosis during Salmonella infection in an enteritis model." (PMID 30248149, 2018). "Here, we report a pleiotropic role for caspase-8 in the control of gene expression downstream of Yersinia and Salmonella infection, as well as all TLRs that we tested, including those that signal through MyD88." (PMID 27737018, 2016). "Ripk3-/-Casp8-/- BMDMs showed dramatically reduced IL-6 and IL-12p40 production compared with B6 or Ripk3-/- cells in response to Yersinia and Salmonella infection." (PMID 27737018, 2016). "Thiol protease, acts as a molecular switch for apoptosis, necroptosis and pyroptosis; Salmonella infection recruits caspase−8 to the inflammasome and regulates interleukin-1β production; Salmonella Typhimurium sseK3 induces caspase 8 activation and modulates macrophage apoptosis and glycolysis." (PMID 41250600, 2025). "In the context of Salmonella infection, it has also been reported that CARD9 negatively regulates IL-1β by fine-tuning pro-IL-1β expression, SYK-mediated NLRP3 activation and repressing inflammasome-associated caspase-8 activity." (PMID 37528097, 2023). "We also noted in these experiments that Casp1–/–;Casp11–/–;Casp12–/– iBMDMs showed more prominent processing of caspase-8 following Salmonella infection compared to WT iBMDMs and that this was accompanied by classical markers of apoptosis, such as cleavage of BID and caspases-3, -7, and -9." (PMID 32735843, 2020). "Whether the Caspase-8/GSDMD pathway is also involved in Salmonella infection deserves deep investigation." (PMID 33384666, 2020). "In that line, Salmonella infection has recently been shown to induce recruitment of both NLRP3 and NLRC4 to the same inflammasome complex along with ASC, caspase-1, and caspase-8." (PMID 28403163, 2017). "Interestingly, C. rodentium infection leads to a similar lethal disease outcome in mice lacking Caspase-8 in the intestinal epithelium as observed during Salmonella infection." (PMID 34497340, 2022). "In Salmonella infection caspase-8 processes IL-1β but does not affect pyroptosis." (PMID 27670879, 2016).
Alzheimer disease (14 papers, 2017 to 2025). A progressive, neurodegenerative disease characterized by loss of function and death of nerve cells in several areas of the brain leading to loss of cognitive function such as memory and language. "In Alzheimer’s disease, caspase-8 and caspase-9 become colonized in the brain, resulting in mitochondrial dysfunction." (PMID 38542318, 2024). "Six of the identified 33 proteins for Alzheimer’s disease in plasma samples corresponded with our findings in serum samples and can now be considered replicated by our study (Casp-8, CXCL5, CXCL6, ST1A1, TRAIL, uPA)." (PMID 36085081, 2022). "Notably, investigations in the brains of Alzheimer’s disease (AD) patients reveal the abundant presence of the active form of caspase-8 specifically within neurons bearing neurofibrillary tangles (NFTs)." (PMID 38254718, 2024). "A similar pattern has been shown in other pathological situations such as in the advanced stage of Alzheimer’s disease, where TNFSF10 secreted by astrocytes binds to TNFRSF10B on neurons and triggers caspase-8-dependent apoptosis." (PMID 34835061, 2021).
head and neck cancer (14 papers, 2011 to 2025). A primary or metastatic malignant neoplasm affecting the head and neck. "In head and neck cancer cell lines, caspase-8 and Bid expression has been shown to be associated with sensitivity to TRAIL." (PMID 36496977, 2022). "CASP8 normally functions as a part of cell apoptosis, and CASP8 mutations have been associated with resistance to apoptosis as well as malignant transformation in head and neck cancer." (PMID 33112566, 2020). "We also found that mutations in the cell death modulator DIDO1 (death obliterator-inducer 1) manifest a similar pattern in to CASP8 in head and neck cancer, with DIDO1 mutations associated with higher estimates of natural killer cells." (PMID 28749946, 2017). "It has been reported that Fas/DR5/FADD/caspase-8 death signaling pathway plays a critical role in regulation of cancer metastasis in human head and neck cancer." (PMID 27286445, 2016). "It was reported that high levels of Fas/DR5/FADD/caspase-8 death signaling play a critical role in regulation of cancer metastasis in human head and neck cancer." (PMID 27286445, 2016). "Pseudolaric acid B induces apoptosis in head and neck cancer cells by activating caspase-8." (PMID 40264676, 2025). "Measuring expression and genotyping caspase-8 in head and neck cancers may be predictive of TRAIL DR agonist efficacy." (PMID 36496977, 2022). "Although it is an intriguing hypothesis that the mutations in cell death pathways (CASP8, DIDO1) observed in head/neck cancer could be a tumor adaptation to ongoing immune activity, additional experiments will be necessary to establish this." (PMID 28749946, 2017). "This suggests that caspase-8 expression or mutation may be a useful biomarker in head and neck cancer, but not across all tumor types including TNBC." (PMID 36496977, 2022). "Moreover, according to a curated set of non-redundant studies in cBioPortal, CASP8 and HRAS mutations, they seem to be generally more frequent in head and neck cancers (9.57% and 5.83%, respectively) than in gastroesophageal adenocarcinomas and squamous cell carcinomas (2.07% and 0.15%)." (PMID 35664801, 2022).
head and neck squamous cell carcinoma (13 papers, 2010 to 2024). A squamous cell carcinoma that arises from any of the following anatomic sites: lip and oral cavity, nasal cavity, paranasal sinuses, pharynx, larynx, and salivary glands. "We next examined the CASP8 mutation status of FASLG expressing tumours in The Cancer Genome Atlas (TCGA) head and neck squamous cell carcinoma (HNSCC) dataset using cBioPortal." (PMID 37443405, 2023). "In particular, mutation of caspase-8 occurs in 10% of head and neck squamous cell carcinoma (HNSCC) tumors, a malignancy associated with tobacco and alcohol consumption and oropharyngeal infection with human papillomavirus." (PMID 34362880, 2021). "To investigate the significance of CASP8 mutations in head and neck squamous cell carcinoma (HNSC), we performed differential gene expression analysis using RNA-seq data from HNSC cases with and without CASP8 mutations." (PMID 30775178, 2019). "In addition, CASP8 cleavage and CASP8, which were also found frequently (11.2%) in head and neck squamous cell carcinomas, are associated with poor overall survival in univariate and multivariate analyses." (PMID 34070941, 2021). "Studies, using next generation sequencing (NGS) method, reported that mutations in CASP8 can vary from 7–34% in head and neck squamous cell carcinoma (HNSCC) across worldwide populations including India." (PMID 32492030, 2020). "EphB4 siRNA significantly inhibited tumor cell viability, induced apoptosis, activated caspase-8, and inhibited the growth of tumor xenografts in vivo in head and neck squamous cell carcinoma." (PMID 32733636, 2020). "Genes CASP8 and FAT1 are reported to co-occur in TCGA-Head and Neck Squamous Cell Carcinoma; however, we observe similar incident in only one out of 11 samples with these SNVs." (PMID 34136393, 2021). "Results showed that oprozomib induced apoptotic pathway through Bik upregulation and activation of caspase-8, caspase-9, caspase-3, and PARP cleavage in head and neck squamous cell carcinoma (HNSCC) cells, leading to cell death." (PMID 29134486, 2017). "In head & neck squamous cell carcinoma cells, the autophagic cargo adapter p62/SQSTM1 is augmenting the activation and full processing of caspase 8 by capturing ubiquitinated caspase 8 into aggresome-like structures, necessary for subsequent apoptosis induction upon radiation treatment." (PMID 36596765, 2023). "We recently reported that the reconstitution of procaspase-8 is sufficient for sensitizing cisplatin- but not etoposide-induced apoptosis, in chemoresistant and caspase-8 deficient HOC313 head and neck squamous cell carcinoma (HNSCC) cells." (PMID 21801448, 2011).
ischemia (13 papers, 2015 to 2025). A hypoperfusion of the BLOOD through an organ or tissue caused by a PATHOLOGIC CONSTRICTION or obstruction of its BLOOD VESSELS, or an absence of BLOOD CIRCULATION. "Whether Fas leads to caspase-8 activation and apoptotic death mainly in neurons or oligodendrocytes might depend on the type of injury (contusion/transection vs. clip compression, which causes a more severe ischemia)." (PMID 29666570, 2018). "Isorhamnetin reduces activation of the extrinsic apoptotic pathway by decreasing caspase-3 and caspase-8 in the cell model of ischemia-induced cerebral vascular degeneration." (PMID 39106233, 2024). "The increased expression of apoptosis-related proteins cleaved Casp3 and Casp8 was found in the retina of the ischemia-injured rats (1.81 and 1.63 folds, respectively, p < 0.05) when compared to that of the uninjured normal rats." (PMID 31379990, 2019). "Expressions of activated caspase-3 and caspase-8, Sod2, and inflammation-related proteins as well as p38 phosphorylation were significantly upregulated in the ischemia-injured rats." (PMID 31379990, 2019). "In hippocampal cultures subjected to ischemia, inhibitors of caspase-8, caspase-9, and p38 MAPK decreased caspase-3 activity to 95%, 94% and 108%, respectively." (PMID 30778709, 2019). "In the presence of caspase-8 and caspase-9 inhibitors (40 μM), the ischemia-induced LDH release was diminished to 212% and 220%, respectively." (PMID 30778709, 2019). "The levels of three core components of necrotic pathways, RIPK1, RIPK3 and MLKL significantly increased during 6–24 h of ischemia developed after the beginning of reperfusion, while cleaved caspase-8 was reduced." (PMID 30158627, 2018). "In our research, we found that the role of extrinsic apoptosis pathway is inactivated due to the sustained low caspase-8 activity in AKT2-inhibited cardiomyocytes during ischemia." (PMID 28272306, 2017). "In the setting of focal ischemia, CASP8 expression has previously been observed in neurons after cerebral infarction, and the present data point to an important role for CASP8 in the neuropathology of ischemia." (PMID 26539914, 2015). "Inhibition of HMGB1 significantly suppressed the expression of cleaved caspase-8 in ischemia retinal tissue." (PMID 26224068, 2015). "Together, these results reveal that CASP6 and CASP8 have an important role in the degeneration of retinal ganglion cells after ischemia." (PMID 26539914, 2015). "To evaluate the possible neuroprotective effects of CASP6 or CASP8 knockdown, we injected siRNAs into the vitreous chamber of the eye after ischemia." (PMID 26539914, 2015). "It was also demonstrated that miR-133b-5p contributes to hypoxic preconditioning-mediated cardioprotection by inhibiting the activation of caspase-8 and caspase-3 apoptotic signalling, thereby reducing cardiomyocyte apoptosis following ischemia/reperfusion injury in vivo." (PMID 40786048, 2025). "After showing that CASP6 or CASP8 inhibition ameliorated the neuropathological consequences of ischemia, we evaluated whether these interventions affect caspase activation in the brain and retina." (PMID 26539914, 2015). "Although Caspase 8 expression was not affected by hyperoxia, its expression was significantly increased, especially in Ripk3−/− mice with ischemia and increased neovascularization during OIR." (PMID 39768199, 2024). "But, interestingly, after cerebral ischemia there is an upregulation of Fas and the FasL, suggesting that FasL release after SC ischemia could induce the formation of DISC and caspase-8 activation in neurons." (PMID 29666570, 2018).
esophageal cancer (12 papers, 2014 to 2025). A primary or metastatic malignant neoplasm involving the esophagus. "At present, the expression of CASP8 in esophageal cancer remains elusive and needs extensive studies." (PMID 36533709, 2023). "We, that the expression levels of CASP8 mRNA were considerably increased in different cancer types, including bladder urothelial carcinoma, esophageal carcinoma, stomach adenocarcinoma, etc.." (PMID 36466844, 2022). "Gain-and-loss-function experiments indicated that miR-338 suppressed expression of CST3 protein (also Cystatin C, CysC), promoted expression of apoptotic proteins caspase-8/3, attenuated esophageal carcinoma cell growth and induced its apoptosis." (PMID 28423738, 2017). "At present, there are only a few studies on CASP8 in esophageal cancer." (PMID 36533709, 2023). "MG132 can significantly enhance the sensitivity of esophageal cancer cells to cisplatin and effectively improve the rate of cell apoptosis by inhibiting the activation of NF-κB, potentiating the expression levels of apoptosis-related protein caspase-8 and -3." (PMID 24584782, 2014). "In esophageal carcinoma cells, ARL6IP5-OE induced apoptosis through Caspase-8 and Caspse-9, the key executioners of the extrinsic and intrinsic apoptosis pathways, respectively." (PMID 35293383, 2022).
esophageal squamous cell carcinoma (12 papers, 2014 to 2025). Esophageal squamous cell carcinoma (ESCC) is a type of esophageal carcinoma (EC) that can affect any part of the esophagus, but is usually located in the upper or middle third. "Caspase-8 (CASP8) is an essential initiator of apoptosis and is associated with many diseases in humans including esophageal squamous cell carcinoma." (PMID 24819879, 2014). "Interestingly, recent data from literature highlighted a functional link in esophageal squamous cell carcinoma between Caspase-8 point mutations, frequently identified in this tumor, and the aberrant NRF2 activation that allows cancer cells to cope with oxidative stress and metabolic rewiring." (PMID 41053176, 2025). "In esophageal squamous cell carcinoma, photodynamic therapy induces pyroptosis by activating caspase-8, indicating caspase-8 as a new target for esophageal squamous cell carcinoma." (PMID 36105400, 2022). "It has been reported that dihydroartemisinin (DHA), a conventional drug to kill malaria parasites, can induce pyroptosis of esophageal squamous cell carcinoma (ESCC) cells via PKM2 caspase-8/3-GSDME pathway, providing a potential therapeutic agent for the treatment of ESCC." (PMID 35517821, 2022). "ATF4 activates the transcription factor CHOP and then transcriptionally activates death receptor 5 (DR5) and caspase 8, which ultimately induces the extrinsic apoptosis of esophageal squamous cell carcinoma (ESCC) cells." (PMID 37006236, 2023). "In esophageal squamous cell carcinoma (ESCC), the pyruvate kinase M2 (PKM2)-caspase 8/3-GSDME pathway induces pyroptosis in ESCC cells." (PMID 37705746, 2023). "In the context of esophageal squamous cell carcinoma (ESCC), photodynamic therapy (PDT) has been shown to directly inhibit PKM2, thereby activating the PKM2/caspase-8/caspase-3/GSDME axis." (PMID 41169372, 2025).
Ewing sarcoma (12 papers, 2003 to 2016). A small round cell tumor that lacks morphologic, immunohistochemical, and electron microscopic evidence of neuroectodermal differentiation. "Treatment with viscum or viscumTT induced apoptosis in a concentration-dependent manner in primary Ewing sarcoma cells ex vivo, leading to mitochondrial membrane depolarization and CASP8 and CASP9 activation." (PMID 27589063, 2016). "The prognostic value of proliferation index (PI) and apoptotic index (AI), caspase-8, -9 and -10 expression have been investigated in primary Ewing's sarcoma family of tumours (ESFT)." (PMID 25157404, 2014). "TRAIL-resistant Ewing's sarcoma was shown to have low levels of caspase-8 both in mRNA and protein levels." (PMID 12610517, 2003). "Therefore, we analyzed the activation and activity of caspase-8 to confirm activation of the receptor-mediated pathway of apoptosis in human Ewing’s sarcoma cells." (PMID 27547487, 2014). "Expression of CASP8 is reduced in ∼24% of tumours from patients with Ewing's sarcoma." (PMID 20221256, 2010). "If this hypothesis is true, a caspase 8 inhibitor would be expected to protect Ewing tumour cells from FGF2-induced apoptosis." (PMID 15685229, 2005). "Downregulation of caspase-8 was also reported in TRAIL-resistant Ewing's sarcoma cells." (PMID 12610517, 2003). "SOX2 advanced Ewing’s sarcoma cell survival and proliferation by regulating p21, p27 and cyclin-E to facilitate G1/S phase transition and mediating caspase-3, PARP via both extrinsic (Fas and caspase-8) and intrinsic (caspase-9, Bad, Bcl-2 and XIAP) apoptotic pathways to restrain cell apoptotsis." (PMID 26969300, 2016).